SELENOP (selenoprotein P)
Diseases named in the same sentence as SELENOP in open-access papers (continued):
Sharing a sentence is not in itself a finding about the gene and the disease.
cancer (continued). "Through our analysis, we confirmed higher levels of GPX2 and TXNRD1, and lower levels of GPX1, SELENOF, and SELENOP in the cancer cell lines compared to normal epithelial cells, which has already been observed and reported in the literature." (PMID 32933107, 2020). "Selenium is generally transported by selenoprotein P (SEPP1) and its mutations and/or haplo insufficiency increases genomic instability and risk of cancer." (PMID 32426284, 2020). "SELENOP, another Se-dependent protein, is pivotal in cancer progression and therapeutic responses." (PMID 39942544, 2025). "SELENOP’s role across multiple cancers suggests its importance in cancer biology and prognosis." (PMID 39942544, 2025). "Importantly, selenoprotein P shows potential as a predictor of patient survival and as a biomarker for hypoxia, a condition affecting cancer progression." (PMID 39001444, 2024). "Furthermore, recent research suggests that high-intensity interval training (HIIT) can significantly increase levels of selenoprotein P (SEPP1), a biomarker associated with cancer prevention, neurological function, and dopamine signaling." (PMID 39519153, 2024). "Notably, SELENOP levels were lower in high-grade (G3–G4) compared to low-grade (G1) cancers, suggesting a correlation with cancer severity." (PMID 39001444, 2024). "Moreover, changes in the expression of SELENOP, Sep15, GPx1, GPx2, and TrXR1 (thioredoxin reductase 1) have been related to different forms of cancer." (PMID 37895024, 2023). "While SELENOP expression was still lower in MSS cancers than in differentiated epithelial cells, we hypothesize that SELENOP upregulation throughout progression to malignancy fortifies tumor-promotive WNT signaling activity." (PMID 37166989, 2023). "Elevated Se uptake via SELENOP suggests that cancer cells may require selenoprotein synthesis to render themselves resistant to ferroptosis." (PMID 36358931, 2022). "Cancer cells may increase the uptake of Se through system Xc− or as SELENOP through LRP8 receptor to protect the cell from ferroptotic cell death, while also modulating key enzymes of the trans-selenation pathway, such as CBS, CGL, or SCLY." (PMID 36358931, 2022). "Namely, in comparisons with bulk normal colon tissues, we believe strong SELENOP expression in stromal and differentiated epithelial cells obscures the detection of meaningful, albeit subtle, differences in SELENOP expression from tumor-initiating cells to polyps and cancers." (PMID 37166989, 2023). "SELENOP and CD244 were highly expressed in the adjacent cancer tissues, while PKMYT1 and LAG3 were highly expressed in the cancer tissues." (PMID 40821907, 2025). "We found significant differences in the expression of SELENOP, PKMYT1, LAG3 and CD244 between the cancer tissues and adjacent cancer tissues." (PMID 40821907, 2025). "Our analyses revealed increases in SELENOP expression from tumor-initiating stem cells to adenomatous polyps and MSS cancers." (PMID 37166989, 2023). "By contrast, the FN1-related molecular pairs, including FN1-CD44 (a marker of cancer stem cells) and FN1-(ITGAV + ITGB1), were prompted between SELENOP-Mφ/SPP1-Mφ and FABP4-Mφ/FCN1-Mφ/CD4/CD8 cells in LUAD." (PMID 36008393, 2022). "Overall, it is demonstrated that two selenoproteins, SELENOF (SelF) and SELENOP (SelP), are only positively correlated with ZIP8 across multiple cancer types (23/40 and 19/40, respectively)." (PMID 34768831, 2021). "In this study, changes in gene expression were observed for SELENOP, SELENOS, and TXNRD3 for all sample groups, while GPX4 was significant in the Irish cancers only and GPX1, SELENOH, and SELENON were differently regulated in the Czech CRCs." (PMID 30469315, 2018). "In this respect, functionally important cancer-related SNPs have been reported in several selenoprotein genes including GPx1, GPx4, TXNRD1 and the circulating Se transport protein selenoprotein P (SePP)." (PMID 23056383, 2012).
cancer (continued). "Here, we observed high SELENOP expression in subsets of ASCs, SSCs, and MSS cancer cells." (PMID 37166989, 2023). "Among these, selenoprotein P (SELENOP) and plasma glutathione peroxidase (GPX) are the most abundant species, and they play a relevant role for health status for the prevention of inflammation, cardiovascular diseases, infections, and cancer." (PMID 37432362, 2023). "Moreover, high expression of SEPP1 (SELENOP) was also observed in endothelial and epithelial/cancer populations." (PMID 37848457, 2023). "As a critical catalytic residue in enzymes such as GPx, TrxR, and selenoprotein P (SELENOP), selenocysteine contributes to a range of physiological processes, including cellular protection against aging, the modulation of inflammatory responses, and defense against cancer." (PMID 40867560, 2025). "Unlike in conventional CRCs, SELENOP expression was increased in serrated polyps, but not MSI-H cancers, as compared with tumor-initiating absorptive cells." (PMID 37166989, 2023).
tumor (43 papers, 2010 to 2026). "Specifically, a higher age showed a borderline protective effect on tumor grade in SELENOP heterozygotes (p = 0.051), while the association with age was reversed among homozygotes." (PMID 41563517, 2026). "SELENOP encodes for a selenoprotein that mediates microenvironmental changes that influence tumor growth and prognosis across multiple solid tumors such as prostate and breast cancers." (PMID 37798266, 2023). "The residual blast cells depicted overexpression of multiple genes associated with tumor growth (SELENOP), metabolism, and stemness (HOPX, FAM30A)." (PMID 37798266, 2023). "Interestingly, when patients were stratified based on tumor-associated increases or decrease in SELENOP expression relative to their own normal tissue, most other selenoproteins were consistently upregulated in tumors in both subgroups." (PMID 40818321, 2025). "Whether and in how far SELENOP acts as a tumour associated antigen promoting autoimmunity or whether the SELENOP-aAb rather constitute a risk factor contributing to the higher prevalence in this cohort must be investigated in further studies." (PMID 35636018, 2022). "Within a publicly available single-cell transcriptomic dataset of HCC tumors, we identified a tumor cluster (HCC1) with low SELENOP expression and high NRF2 activity." (PMID 40818321, 2025). "In this study, we reanalyzed publicly available single-cell RNA sequence data of HCC tumors and identified a distinct tumor cell cluster characterized by reduced SELENOP expression, enhanced GPX4 and TXNRD1 expression, and activation of NRF2 signaling." (PMID 40818321, 2025). "These receptors, with additional functions impacting tumour growth, highlight the complexity of SELENOP’s role." (PMID 39001444, 2024). "On the other hand, the other two groups exhibited high expression of CCL4 and SELENOP, both of which have immunosuppressive and tumor-promoting functions." (PMID 38311726, 2024). "In the present study, both SPP1+ Mac and SELENOP+ Mac in MLN were found to promote tumor cell growth and were significantly increased in MLN." (PMID 38755647, 2024). "The EOI residual blast cells depicted overexpression of multiple genes associated with tumor growth and poor outcome including HOPX, SELENOP/SEPP1, and FAM30A/C1orf11053–55." (PMID 37798266, 2023). "In this study, we delineated tumor-promotive roles for SELENOP in sporadic CRC through amplification of canonical WNT signaling activity via specific interactions with LRP5/6." (PMID 37166989, 2023). "Patients that died over the course of the follow-up were older at time of diagnosis, more frequently post-menopausal, had larger tumours, more lymph nodes involved, lower serum Se and SELENOP concentrations and a lower serum GPx3 activity." (PMID 37741974, 2023). "Altogether, these results propound tumor-promotive roles for SELENOP in Apc-dependent tumorigenesis." (PMID 37166989, 2023). "CCL18+M1, CXCL9+M2, and TIMP1+M3 were enriched in tumor tissues and were regarded as TAMs, whereas SELENOP+M4, MMP7+M5, CHIT1+M6, and PPARG+M7 were enriched in normal tissues and considered as resident tissue macrophages (RTMs)." (PMID 34659209, 2021). "Four cell types, SELENOP+M4, CXCL9+M2, CD1C+DC1, and CLEC9A+DC2, were negatively associated with tumor progression (FDR < 0.05)." (PMID 34659209, 2021). "Research in mammals suggests that the acute phase response (APR), defined as “a complex systemic early-defense system activated by trauma, infection, stress, neoplasia, and inflammation”, inhibits selenoprotein P production (reviewed by Burk and Hill)." (PMID 26610852, 2015). "To resolve this discrepancy between transcript and protein levels, we hypothesized that SELENOP suppression may occur within a specific subpopulation of tumor cells." (PMID 40818321, 2025). "Finally, multivariate analysis for OS including the tumor stage showed independent prognostic value for the combined tumor expression of SELENOP and GOS2 (p = 1.55E-05, Wald test)." (PMID 38167013, 2024).
tumor (continued). "However, another study suggested that SELENOP+ Mac was similar to M2-type macrophages and had a role in promoting tumor growth." (PMID 38755647, 2024). "Ligand APP from tumor cells and fibroblasts might increase the expression of SELENOP in macrophages." (PMID 38044943, 2023). "To test this hypothesis, we simultaneously analysed three complementary biomarkers of Se status (total serum Se, SELENOP, GPx3) and conducted bulk RNA-sequencing of tumours of 1453 patients with a new diagnosis of primary invasive breast cancer." (PMID 37741974, 2023). "Similarly, SELENOP was overexpressed in tumor tissues, where it may promote tumor growth through increased inflammation and oxidative stress." (PMID 41244925, 2025). "Thus, we aimed to evaluate the effects of dietary Se supplementation (SeMet and Brazilian nuts) on tumor growth, blood Se levels, hepatic GPx activity, SELENOP expression, and tumor and metastatic histomorphology in a 4T1 mouse breast cancer model starting consumption after tumor detection." (PMID 36634075, 2023). "The spatial co-localization of KLK6-positive cells with SELENOP+ and SPP1+ macrophages is also particularly noteworthy, as these subsets are known to exhibit immunosuppressive properties and promote tumor angiogenesis." (PMID 41383634, 2025). "SELENOP, SELENBP1, and SOD2 had medium protein expression levels, in both the normal and the tumor cells." (PMID 30469315, 2018). "This signature not only effectively stratifies patient risk but also delineates specific molecular pathways, such as those involving SELENOP, CDKN2A, and PGR, through which the diabetic milieu may drive tumor aggressiveness." (PMID 41244925, 2025). "Paired t-test analysis confirmed no significant change in SELENOP expression, while 21 out of 25 selenoprotein genes showed significantly increased expression in tumor tissues compared to matched normal tissues." (PMID 40818321, 2025). "Selenop-KO tumor organoids demonstrated defects in organoid formation and decreases in WNT target gene expression, which could be reversed by SELENOP restoration." (PMID 37166989, 2023). "We have defined the top 5 marker genes (ADH1B, CFD (DF), SEPP1 (SELENOP), DCN, and A2M) that could be used for the identification of ADH1B+ CAFs in tumor tissues." (PMID 37848457, 2023). "As expected in conditions of redox stress, a lowered SELENOP expression was reported in studies of a small number of German CRA and CRC subjects, while heterogenous GPX2 mRNA and protein expression was observed between the tumor samples." (PMID 30469315, 2018). "In addition, the diets also did not alter tumor or prostate androgen receptor, probasin, selenoprotein 15, selenoprotein P, or selenium binding protein 2 mRNA expression." (PMID 20454690, 2010).
cardiovascular disease (12 papers, 2019 to 2025). "A decrease in circulating levels of SELENOP was also associated with a greater risk of metabolic syndrome in patients with documented cardiovascular disease." (PMID 34639053, 2021). "Furthermore, low plasma Se and SELENOP concentrations are associated with the risk of developing cancer and cardiovascular diseases." (PMID 32131476, 2020). "Given the role of SELENOP as functional marker of Se status and availability, and the need for a large enough group of healthy subjects with sub-optimal Se supply, we tested the association of SELENOP with cardiovascular disease in a large European prospective cohort study." (PMID 31404994, 2019). "Several studies describe that Se incorporated into selenoprotein p protects the oxidation of n−3 PUFAs and inflammation in cardiovascular disease." (PMID 39273236, 2024). "Studies on SELENOP knockout (KO) mice underline the essential role of SELENOP in delivering Se to the brain and testes; however, the data on SELENOP significance in cardiovascular disease are scarce." (PMID 37371917, 2023). "Despite this clinical association, it is unclear if SELENOP is indeed necessary to prevent cardiovascular disease, as SELENOP KO mice subjected to I/R injury exhibited significantly reduced infarct sizes, indicating that less tissue was damaged, and cardiac apoptosis compared to WT mice." (PMID 34639053, 2021). "Selenoprotein P (SeP) is mainly synthesized in the liver and appears to show upregulated expression in the liver of patients with T2D, NFALD, and cardiovascular disease." (PMID 31405033, 2019).
metabolic disorders (9 papers, 2018 to 2025). "This may be due to the fact that in metabolic disorders, SELENOP inhibits the burst of ROS required for normal insulin signaling due to the powerful reducing effect of SELENOP, so this condition is also known as reductive stress." (PMID 40437610, 2025). "Furthermore, high levels of Selenoprotein P (SeP) are found in patients with metabolic diseases, positively correlating with insulin resistance." (PMID 38612504, 2024). "On the other hand, insulin exerts inhibitory effects on the gene expression of SELENOP in hepatocytes, and impaired insulin action in certain metabolic disorders might increase the expression and circulating level of SELENOP." (PMID 35883754, 2022). "Interestingly, circulating SELENOP is studied as a potential mediator of metabolic disorder and, although mechanisms involving the pancreas and BAT were reported, the physiological effects of SELENOP in the hypothalamus were not reported on." (PMID 36499772, 2022). "Overproduction of SELENOP and the development of metabolic disorders might reinforce each other in a vicious cycle." (PMID 30425271, 2018). "Therefore, the overproduction of SELENOP and the development of metabolic disorders might reinforce one another mutually in a vicious cycle, and SELENOP is a multifunctional protein in the pathology of GLMDs." (PMID 35883754, 2022).
infection (8 papers, 2009 to 2025). The state of being infected such as from the introduction of a foreign agent such as serum, vaccine, antigenic substance or organism. "In this regard, macrophages expanding in the liver of T. congolense—infected mice expressed higher level than Ly6C- monocytes of the M2-type gene selenoprotein P (Sepp1), that we documented to exert anti-oxidant hepatoprotective function during infection." (PMID 26020782, 2015). "It is a constituent of 25 selenoproteins, including thioredoxin reductases, glutathione peroxidases and selenoprotein P. Selenoproteins play a crucial role in thyroid hormone metabolism, DNA synthesis, reproduction and protection from oxidative damage and infection." (PMID 40944226, 2025). "The following research was conducted to elucidate the evolution and expression of salmonid selenoprotein P (SelP), a selenoprotein that is unique in having multiple selenocysteine (Sec) residues, following supranutritional selenium supplementation and infection in rainbow trout." (PMID 30571741, 2018).
colorectal (4 papers, 2018 to 2023). "Overall, these results suggest that upregulation of SELENOP expression throughout conventional colorectal carcinogenesis occurs as a function of stemness." (PMID 37166989, 2023). "SELENOP expression progressively increases throughout conventional colorectal carcinogenesis." (PMID 37166989, 2023). "However, the contribution of selenoprotein P (SELENOP), a unique selenocysteine-containing protein, to sporadic colorectal carcinogenesis challenges this paradigm." (PMID 37395277, 2023).
degenerative diseases (2 papers, 2006 to 2022). "Therefore, despite some partial correlation between blood and CSF selenoprotein P content, only the latter appear to be linearly associated with the risk of the two major neurodegenerative diseases investigated in this study, ALS and AD, though in an entirely different direction." (PMID 36077261, 2022). "This study about selenoprotein P concentrations in individuals affected by neurodegenerative disease is apparently the first ever to have been carried out in vivo and using a biomarker within the central nervous system, in addition to the serum levels of this protein." (PMID 36077261, 2022).
inflammation (1 paper, 2022). Aberrant reaction of the microcirculation characterized by movement of fluid and leukocytes from the blood into extravascular tissues. "Lower SELENOP levels in patients with definite NASH may be the downregulation of SELENOP in this condition characterized by liver inflammation." (PMID 36267567, 2022).
SELENOP also shares sentences with these, for which no sentence is quoted: autoimmune thyroid disease (5 papers); neurological disease (4); prostate tumors (4); cerebellar ataxia (3); abdominal aortic aneurysm (2); acute kidney injury (2); adenocarcinoma (2); colorectal tumor (2); depression (2); endothelial dysfunction (2); hepatitis C (2); insulinoma (2); ischemia (2); myocardial infarction (2); peripheral arterial disease (2); Abdominal obesity (1); aneuploidy (1); aneurysm (1); Atrophy (1); bacterial infection (1); bladder cancer (1); breast adenocarcinoma (1); Cerebral atrophy (1); Cerebral ischemia (1); cervical cancer (1); clear cell renal cell carcinomas (1); cognitive disorder (1); coronary artery disease (1); dermatosis (1); E. coli infection (1).
A further 50 diseases each share a sentence with SELENOP in 1 paper.